DDA1 (DET1 and DDB1 associated 1)
Description:
Functions as a component of numerous distinct DCX (DDB1-CUL4-X-box) E3 ubiquitin-protein ligase complexes which mediate the ubiquitination and subsequent proteasomal degradation of target proteins. In the DCX complexes, acts as a scaffolding subunit required to stabilize the complex.
Synonyms: C19orf58; PCIA1; MGC2594
Tractability: Small molecule: a structure with a bound ligand is known. PROTAC: ubiquitination databases record sites on it; its protein half-life has been measured.
Gene: Protein-coding gene on chromosome 19 (17,309,518 to 17,323,298, forward strand). Ensembl gene ENSG00000130311.
Subcellular location (Human Protein Atlas): Nucleoli; Nucleoplasm
Pathways (Reactome):
Metabolism of proteins: Neddylation
Gene Ontology:
Molecular function: protein binding
Biological process: protein polyubiquitination; regulation of natural killer cell activation; protein ubiquitination; regulation of proteasomal ubiquitin-dependent protein catabolic process
Cellular component: Cul4-RING E3 ubiquitin ligase complex; Cul4A-RING E3 ubiquitin ligase complex; Cul4B-RING E3 ubiquitin ligase complex; nucleoplasm
Genetic constraint (gnomAD): Loss-of-function variants: 3 observed, 17.06 expected, observed/expected ratio (o/e) 0.18, 90% interval 0.079 to 0.46. The upper end of that interval is the gene's LOEUF score, 0.46, which puts it in group 2 of 6, group 1 being the genes least tolerant of losing a copy. Missense variants: 105 observed, 126.64 expected, observed/expected ratio (o/e) 0.83, 90% interval 0.71 to 0.98. Synonymous variants: 52 observed, 49.89 expected, observed/expected ratio (o/e) 1.04, 90% interval 0.83 to 1.31.
Homologues: Orthologues: chimpanzee DDA1 (100% identical), macaque DDA1 (100% identical), guinea pig DDA1 (99% identical), pig DDA1 (99% identical), mouse Dda1 (98% identical), tropical clawed frog dda1 (89% identical), zebrafish dda1 (88% identical), rat Dda1 (73% identical), Drosophila melanogaster CG31855 (42% identical).
Diseases named in the same sentence as DDA1 in open-access papers:
DDA1 is named in the same sentence as 11 diseases in open-access papers, as found by Europe PMC text mining. Sharing a sentence is not in itself a finding about the gene and the disease. The quoted sentences say what the papers report.
breast carcinoma (2 papers, 2022). "Indeed, the evaluation of an ER+ breast cancer cohort with a 10‐year follow‐up (Table EV6), identified increased AHR, DDA1, and UBE4B levels in the primary tumors that relapsed (EV4O and Q, Table EV7)." (PMID 35174975, 2022).
colon cancer (2 papers, 2016 to 2025). "These discoveries indicate that the underlying mechanism by which DDA1 promotes stage II colon cancer progression is related to canonical activation of the NFκB pathway." (PMID 26942699, 2016). "Further, these results suggest that patients with stage IIB–IIC colon cancer with DDA1-positive expression have a high risk of recurrence and should be considered for stronger chemotherapy regimens." (PMID 26942699, 2016). "We found that positive expression of DDA1 alone or in combination with p65 nuclear translocation correlated with increased risk of tumor recurrence in patients with stage IIB–IIC colon cancer." (PMID 26942699, 2016). "DDA1, together with NFκB status, can aid in determining the risk of tumor recurrence in patients with stage II colon cancer, and may be a potential marker to evaluate chemosensitivity to 5-FU." (PMID 26942699, 2016). "Taken together, these results suggest that DDA1 upregulation and NFκB activation may be associated with both development and recurrence of stage II colon cancer." (PMID 26942699, 2016). "In colon cancer lines, overexpression of DDA1 promoted cell cycle progression and enhanced cell proliferation." (PMID 39905036, 2025). "They found that in patients with stage IIB–IIC colon cancer, positive expression of DDA1 or co-expression with p65 nuclear translocation was associated with a higher risk of tumor recurrence." (PMID 39905036, 2025). "This interpretation is further supported by the analysis of GO and KEGG pathways and the observation that DDA1 also activates other signal pathways in colon cancers." (PMID 26942699, 2016). "After treating colon cancer cell lines with different 5-FU concentrations for 48 h, DDA1 mRNA and protein levels were evaluated." (PMID 26942699, 2016). "We demonstrated here that DDA1 overexpression promotes the EMT of colon cancer cells with changes in cell morphology, along with downregulation of the epithelial protein E-cadherin and upregulation of the mesenchyme molecules N-cadherin and Vimentin." (PMID 26942699, 2016). "In summary, DDA1 promotes the progression of stage II colon cancer through the activation of the NFκB/CSN2/GSK3β pathway." (PMID 26942699, 2016). "We observed that DDA1 predicts tumor recurrence and poor prognosis in patients with stage II colon cancer, especially for patients with stage IIB–IIC disease undergoing post-operative chemotherapy with 5-FU/LV or FOLFOX4." (PMID 26942699, 2016). "Mechanistically, we found that DDA1 promoted proliferation and invasion in colon cancer cells by enhancing and stabilizing p-IKKβ and triggering the phosphorylation and degradation of IκBα followed by the activation of NFκB/CSN2/GSK3β signaling." (PMID 26942699, 2016). "DDA1 overexpression enhanced the invasive and wound-healing capabilities of colon cancer cell lines." (PMID 26942699, 2016). "DDA1 overexpression in colon cancer lines promoted cell proliferation, facilitated cell cycle progression, inhibited 5-FU-induced apoptosis, enhanced invasion, and induced the epithelial-mesenchymal transition." (PMID 26942699, 2016). "Taken together, these results indicate that DDA1 upregulation and NFκB activation are related to recurrence in stage II colon cancer, and DDA1 contributes to the activation of NFκB." (PMID 26942699, 2016). "In the present study, DDA1 overexpression was positively associated with T stage, AJCC stage, and differentiation in patients with stage II colon cancer." (PMID 26942699, 2016). "Taken together, these results indicate that DDA1 promotes the progression of stage IIB–IIC colon cancers by activating the NFκB/CSN2/GSK-3β pathway." (PMID 26942699, 2016). "In the present study, we found that DDA1 promoted colon cancer cell proliferation and positively modulated cell cycle proteins including Ki-67, CyclinD1 and CDK4/6 in vitro and in vivo, which resulted in cell cycle S-phase arrest." (PMID 26942699, 2016).
colon cancer (continued). "As no cell lines were from patients with IIB – IIC colon cancer, the protein levels of DDA1 from eight general colon cancer cell lines and two normal colon epithelial cell lines were analyzed." (PMID 26942699, 2016). "DDA1 mRNA expression was greater in the tumors of all patients with stage II colon cancer than in adjacent normal tissues of 30 randomly selected patients from the cohort." (PMID 26942699, 2016). "This study aimed to investigate whether DDA1 contributes to tumorigenesis and progression of stage II colon cancer via activation of the NFκB pathway." (PMID 26942699, 2016). "DDA1 may be a powerful prognostic indicator and predictor of tumor recurrence risk in patients with stage IIB–IIC colon cancer." (PMID 26942699, 2016). "Therefore, the effects of DDA1 protein on colon cancer cell proliferation and cell cycle progression were investigated using overexpression and knockdown." (PMID 26942699, 2016). "DDA1 showed mainly positive staining in the cytoplasm of tumor cells and was often accompanied by NFκB subunit p65 nuclear translocation in the tumor cells of relapsed patients with stage II colon cancer (1E1–1E4)." (PMID 26942699, 2016). "Notably, only 50% of the patients in this study with stage II colon cancer exhibited DDA1-positive expression in combination with p65 nuclear translocation." (PMID 26942699, 2016). "In addition, the potential for use of DDA1 as a prognostic indicator in patients with other stages of colon cancer should also be explored." (PMID 26942699, 2016). "DDA1, together with NFκB activation status, may serve as a sensitive biomarker for tumor recurrence risk and prognosis in patients with stage IIB–IIC colon cancers." (PMID 26942699, 2016). "DDA1 overexpression inhibited apoptosis in 5-FU-induced colon cancer cells, although DDA1 was not upregulated by 5-FU treatment." (PMID 26942699, 2016). "Immunohistochemical (IHC) staining was used to quantify DDA1 levels as well as NFκB pathway activation, as measured by p65 nuclear translocation, in 101 relapsed and 178 nonrelapsed patients with stage II colon cancer." (PMID 26942699, 2016). "Furthermore, DDA1 alone or in combination with nuclear p65 positive expression predicted poorer DFS and OS, especially in patients with stage IIB-IIC colon cancer." (PMID 26942699, 2016). "Whether DDA1 has prognostic value in patients with stage II colon cancer has not been assessed previously." (PMID 26942699, 2016). "However, whether DDA1 indeed activates the NFκB pathway, thereby promoting tumorigenesis and contributing to colon cancer recurrence, has not been investigated." (PMID 26942699, 2016).
colorectal cancer (1 paper, 2016). A primary or metastatic malignant neoplasm that affects the colon or rectum. "Analysis of Gene Ontology (GO) and Kyoto Encyclopedia of Genes and Genomes (KEGG) pathways suggest that DDA1 may be involved in the development of colorectal cancer, focal adhesions, apoptosis, and activation of the NFκB signal pathway." (PMID 26942699, 2016).
lung adenocarcinoma (1 paper, 2017). A carcinoma that arises from the lung and is characterized by the presence of malignant glandular epithelial cells. "Here, we demonstrated that DDA1 levels were increased in both lung adenocarcinoma and lung squamous cell carcinoma and that high expression of DDA1 was associated with poor prognosis." (PMID 28211159, 2017). "In both lung adenocarcinoma and squamous cell carcinoma, five‐year survival rates were much higher with low expression of DDA1 than with high expression, as assessed by the Kaplan–Meier method (*P < 0.05)." (PMID 28211159, 2017).
lung carcinoma (1 paper, 2017). "We found that the expression of DDA1 in normal lung cells and tissue was significantly lower than that in lung cancer and was associated with poor prognosis." (PMID 28211159, 2017). "The overexpression of DDA1 in lung cancer, based on positivity by IHC, was significantly associated with tumour size (P = 0.002) and AJCC stage (P = 0.016)." (PMID 28211159, 2017). "In summary, in this study, we found that DDA1 is commonly up‐regulated in lung cancer tissue and cell lines and that higher expression level of DDA1 is associated with poor prognosis in patients with lung cancer." (PMID 28211159, 2017). "Taken together, these results indicate that DDA1 promotes the progression of lung cancer by regulating the cell cycle, especially S phase, and cyclins such as cyclin D1/D3." (PMID 28211159, 2017). "Taken together, DDA1, in lung cancer cells, determined the cell proliferative and colony formation abilities in vitro." (PMID 28211159, 2017). "DDA1 promoted lung cancer tumorigenesis in vitro and in vivo; however, the relationship between DDA1 expression and human lung cancer was still unclear." (PMID 28211159, 2017). "Our results also indicated that DDA1 is up‐regulated and positively correlated with poor prognosis in patients with lung cancer." (PMID 28211159, 2017). "Overexpression of DDA1 was observed in most lung cancer samples and all lung cancer cell lines investigated." (PMID 28211159, 2017). "To explore the molecular mechanism of how DDA1 affects lung cancer, we suggested that DDA1 regulates the cyclins, which are the key regulators of cell cycle progression and proliferation." (PMID 28211159, 2017). "In the present study, DDA1 was shown to be responsible for lung cancer cell G1/S transition and cell proliferation through the regulation of cyclin D1, cyclin D3, cyclin E1 and cyclin B1 expression." (PMID 28211159, 2017). "Further evaluation of DDA1 as a target for lung cancer therapy and the molecular mechanism is required using additional preclinical animal models and other approaches." (PMID 28211159, 2017). "To quantitate the protein expression of DDA1, we scored the staining intensity and proportion using five grades and found that DDA1 was significantly higher in lung cancer tissue and adjacent tissue than in normal tissue (**P < 0.01)." (PMID 28211159, 2017). "DDA1 promoted lung cancer cell proliferation, increased cell cycle progression in vitro through G1/S transition and S‐phase acceleration and regulation of cyclins." (PMID 28211159, 2017). "DDA1 as an oncogenic factor could be a target of future therapeutics or could be applied as a predictive marker of lung cancer." (PMID 28211159, 2017). "We further wondered whether DDA1 was dysregulated in lung cancer cell lines compared to normal lung cells." (PMID 28211159, 2017). "This study aimed to investigate whether DDA1 contributes to tumorigenesis and progression of lung cancer." (PMID 28211159, 2017). "We found that enhanced DDA1 expression is common in human lung cancer." (PMID 28211159, 2017). "Therefore, DDA1 may be a potential novel target for lung cancer treatment, and a biomarker for tumour prognosis." (PMID 28211159, 2017). "DDA1 could be a powerful indicator of tumour prognosis in patients with lung cancer." (PMID 28211159, 2017). "However, the function of DDA1 in lung cancer was previously unknown." (PMID 28211159, 2017). "Negative and positive staining of DDA1 in the epithelial cells was observed in the normal lung tissue, whereas DDA1 expression was high in lung cancer and the adjacent region, in most cases." (PMID 28211159, 2017). "To assess the expression of DDA1 in lung cancers, we performed immunohistochemistry (IHC) of DDA1 expression using a commercially available tissue microarray (TMA) containing 118 cases of lung cancer, adjacent tissue and normal tissue." (PMID 28211159, 2017).
lung carcinoma (continued). "To explore whether the expression of DDA1 affects lung cancer growth in vivo, we transplanted A549 cells with or without DDA1 stable overexpression into nu/nu mice." (PMID 28211159, 2017). "Whether DDA1 has prognostic or therapeutic value in patients with lung cancer has not been previously assessed." (PMID 28211159, 2017).
memory impairment (1 paper, 2022). "Previous studies have shown that loss of DopR (dDA1) causes aversive and appetitive memory impairments." (PMID 36250621, 2022).
ovarian carcinoma (1 paper, 2021). A malignant neoplasm originating from the surface ovarian epithelium. "Liu’s study indicated that NR2F6 overexpression was related to poor overall survival and also stimulated DDA1 transcription by binding to the promoter region in ovarian cancer." (PMID 34304715, 2021).
tumor (5 papers, 2016 to 2025). "We also demonstrated that DDA1-mediated tumor progression is associated with the activation of the NFκB/COP9 signalosome 2(CSN2)/glycogen synthase kinase3β (GSK3β) pathway." (PMID 26942699, 2016). "For example, in the P group, chromosomal region 19p13 is the most frequently gained region: A gene encoded by this region is DDA1, which may be involved in the activation of nuclear factor kappaB (NFκB) and tumor progression." (PMID 31795313, 2019). "Deficiency in DDA1 significantly inhibited tumour growth, based on reductions in both tumour volume (shMock: 1468 ± 193.8 mm3versus shDDA1: 443.6 ± 151.8 mm3, n = 5, P < 0.001) and tumour weight (shMock: 1.226 ± 0.193 g versus shDDA1: 0.322 ± 0.121 g, n = 5, P < 0.01)." (PMID 28211159, 2017). "DDA1 overexpression promoted proliferation of lung tumour cells and facilitated cell cycle progression in vitro and subcutaneous xenograft tumour progression in vivo." (PMID 28211159, 2017). "Up‐regulation of DDA1 accelerated tumour growth in vivo (tumour volume: Mock: 631.6 ± 131.3 mm3versus DDA1: 1080 ± 116.0 mm3, n = 5, P < 0.05; and tumour weight: Mock: 0.566 ± 0.091 g versus DDA1: 0.950 ± 0.106 g, n = 5, P < 0.05)." (PMID 28211159, 2017). "In vivo studies determined that overexpression of DDA1 can promote the tumour growth, while inhibition of DDA1 gene expression can significantly inhibit the tumour growth in subcutaneous xenograft model." (PMID 28211159, 2017). "The results in vitro show that the DDA1 enhances proliferation in tumour cells and promotes S‐phase entry through the regulation of cell cycle‐related proteins." (PMID 28211159, 2017). "In vivo, the overexpression or knockdown of DDA1 in cells generated larger or smaller xenografts, respectively, as measured by tumor weights and volumes in nude mice as compared to controls (P < 0.05)." (PMID 26942699, 2016). "Further, DDA1 protein levels and the nuclear translocation of p65 protein, an indication of activation of NFκB, were also higher in tumor samples than in adjacent normal tissues, and in relapsed patient samples than in nonrelapsed samples." (PMID 26942699, 2016). "In vivo, xenografted DDA1-overexpressing tumor cells had lower E-cadherin levels, but higher expression of nuclear β-catenin, N-cadherin, vimentin, and Snail than controls." (PMID 26942699, 2016). "Suppression of DDA1 inhibited tumor progression, and reduced tumor growth in vivo." (PMID 26942699, 2016). "DDA1 and nuclear p65 staining were positively correlated with pT stage, American Joint Committee on Cancer (AJCC) stage and tumor differentiation in patients with stage II cancer (P < 0.05)." (PMID 26942699, 2016). "Additionally, AHR, DDA1, and UBE4B protein were detected in all tissue samples analyzed from an additional cohort of brain metastases independently of primary tumor source and the presence of clinically validated HSP90‐dependent oncogenes (Table EV5)." (PMID 35174975, 2022). "More importantly, DDA1-positive expression incidence was significantly higher in the recurrent tumor group than in the non-recurrent group." (PMID 26942699, 2016). "A significantly higher proportion (65.4%) of relapsed patients showed strong tumor DDA1 staining as compared to nonrelapsed patients (29.8%)." (PMID 26942699, 2016). "The number of relapsed patients with weak (28.7%) and negative (5.9%) tumor DDA1 staining was significantly lower than the number of nonrelapsed patients with weak (40.4%) and negative tumor staining (29.8%)." (PMID 26942699, 2016).
cancer (4 papers, 2016 to 2022). A tumor composed of atypical neoplastic, often pleomorphic cells that invade other tissues. "DDA1 was expressed in the cytoplasm and nucleus, and its expression in cancer epithelial and stromal regions varied." (PMID 28211159, 2017). "To determine how DDA1 affects cancer cell prognosis and cell survival in vitro, we assessed the cell proliferation rate by CFDA‐SE (5‐(and‐6)‐carboxyfluorescein diacetate, succinimidyl ester) staining and flow cytometry." (PMID 28211159, 2017). "Consistently, DDA1 knockdown with shDDA1#2 suppressed the cancer cell proliferation in vitro and in vivo." (PMID 26942699, 2016). "In the study, we found that both protein and mRNA were higher in cancer cell lines than in normal cells, while DDA1 mRNA was not positively associated with protein level and the mechanism was still unclear." (PMID 28211159, 2017).
DDA1 also shares sentences with these, for which no sentence is quoted: lung squamous cell carcinoma (1 paper); squamous cell carcinoma (1).